TBC1D24 (TBC1 domain family member 24)
Diseases named in the same sentence as TBC1D24 in open-access papers (continued):
Sharing a sentence is not in itself a finding about the gene and the disease.
infection (5 papers, 2017 to 2024). The state of being infected such as from the introduction of a foreign agent such as serum, vaccine, antigenic substance or organism. "The effect of TBC1D24 or SV2B KO on ADE efficiency wasnot overcome even under a high multiplicity of infection conditions used in ourscreens." (PMID 39377586, 2024). "Inaddition to their role in promoting efficient ADE, SV2B, and TBC1D24 may play aminor role in direct infection." (PMID 39377586, 2024). "Furtherstudies using additional clones will be required to clarify the relativecontribution of SV2B and TBC1D24 to ADE and direct infection." (PMID 39377586, 2024). "FcgRIIa-KO, TBC1D24-KO, and SV2B-KO K562-DCSIGN clones reduced the efficiency of direct infection to relatively similar levels compared to the unedited (WT) K562-DCSIGN cell pool, (median reduction of 33%, 27%, 24%, respectively)." (PMID 38712102, 2024). "It is possible that infection with DENV via ADE upregulates the otherwise limited endogenous expression of TBC1D24 and SV2B proteins in non-neuronal cells." (PMID 38712102, 2024). "Next, to confirm that the roles of TBC1D24 and SV2B are unique to IgG-mediated infection, we generated corresponding clonal KO lines in K562 cells engineered to express DCSIGN (K562-DCSIGN), a cellular attachment factor that permits direct DENV infection in the absence of IgG antibodies." (PMID 38712102, 2024). "One limitation of our study is that although we validated the requirement of TBC1D24 and SV2B for efficient ADE in multiple cell lines, we were unable to confirm our findings in primary cells due to difficulty in maintaining cell viability following CRISPR editing and subsequent infection via ADE." (PMID 38712102, 2024).
neurodevelopmental disorder (4 papers, 2020 to 2025). A behavioral and cognitive disorder with onset during the developmental period that involves impaired or aberrant development of intellectual, motor, or social functions. "The TBC and LysM Domain containing (TLDc) proteins containing the structural domain of TBC1 domain family member 24 (TBC1D24) are associated with neurodevelopmental disorders and are mainly involved in the oxidative stress response." (PMID 36915078, 2023). "The F251L knock-in mice represent a useful animal model for investigation of the mechanistic link between TBC1D24 loss-of-function and neurodevelopmental disorders." (PMID 32004315, 2020). "In addition, variants in a Rab35 GAP, TBC1D24, have been associated with a spectrum of neurodevelopmental disorders in a cohort of patients." (PMID 38432637, 2024).
metabolic disorders (3 papers, 2021 to 2024). "In addition, the 4 VUS identified in this study (CFTR: rs1800120, TBC1D24: rs754558646, HTT: rs779780620, and FDX2: rs897162037) were found to coexist with several other P/LP variants or VUS in genes associated with cardiovascular/metabolic diseases or CoQ deficiency." (PMID 38844616, 2024).
tumor (1 paper, 2020). "We observed a higher mRNA expression of TBC1D10C, TBC1D4, TBC1D12, TBCK, TBC1D5, TBC1D30 and a lower expression of TBC1D24 in patients with tumor compared with tumor free patients." (PMID 33194704, 2020).
TBC1D24 also shares sentences with these, for which no sentence is quoted: myoclonic epilepsy (6 papers); developmental delay (5); infantile epileptic encephalopathy (5); Hearing impairment (3); Down syndrome (2); mastitis (2); nonsyndromic deafness (2); Parkinson disease (2); abscesses (1); adenoma (1); Alzheimer disease (1); Arnold-Chiari malformation (1); autism (1); autosomal dominant deafness (1); autosomal recessive deafness (1); biotinidase deficiency (1); Bovine mastitis (1); cerebellar ataxia (1); Dyskinesia (1); encephalitis (1); episodic ataxia (1); Flavivirus Infections (1); Hartnup disease (1); iron deficiency (1); maple syrup urine disease (1); Martsolf syndrome (1); microcephaly (1); mitochondrial disease (1); Myoclonus (1); ophthalmoplegia (1).
A further 11 diseases each share a sentence with TBC1D24 in 1 paper.